MTOR (mechanistic target of rapamycin kinase)
Diseases named in the same sentence as MTOR in open-access papers (continued):
Sharing a sentence is not in itself a finding about the gene and the disease.
carcinoids (8 papers, 2012 to 2024). "In terms of therapeutic targets, PI3K/AKT/mTOR pathway mutations have been described in 13% of typical carcinoids (TCs) and 39% of atypical carcinoids (ACs), representing a targetable mutation with kinase inhibitors." (PMID 35158788, 2022). "The association of mTOR-targeting miRNAs expression with specific tumor characteristics was assessed in the subgroup of carcinoids, only." (PMID 29938004, 2018). "Similarly, components of the PI3K/AKT/mTOR pathway showed a mutation rate higher in carcinomas than in carcinoids (11.7% versus 2.3%; p = 0.031)." (PMID 27873319, 2017). "While it is true that the cell viability methods used in each study were different and the treatment in the present study involved not only PI3K/mTOR inhibitors but also lanreotide, it is also true that H720 cells are of atypical carcinoid origin." (PMID 38375032, 2024). "For the first time, this study describes that a second-generation mTOR pathway inhibitor can result in highly durable tumor regression and control of NET carcinoid symptoms." (PMID 31527867, 2019).
cervical tumors (8 papers, 2009 to 2025). "Nonetheless, misregulation of mTOR in LKB1-deficient tumors may present opportunities for targeted therapy (e.g. through the use of metformin or rapamycin analogs) in women whose cervical tumors have confirmed LKB1 mutations/deletions, an idea that merits further investigation in the future." (PMID 19340305, 2009). "This improved response was especially notable in rectal, bladder, and cervical tumors harboring PI3K/AKT/mTOR pathway alterations." (PMID 39908697, 2025). "All these results strongly suggest that HPV16 E6 rescues IRF-1-triggered apoptosis by interfering with the PI3K/PDK1/mTOR signalling pathway in cervical tumour cells." (PMID 33076322, 2020). "(d) HPV16 E6 activates the phosphorylation of PI3K/mTOR signalling components resulting in angiogenesis of cervical tumour." (PMID 33076322, 2020). "Collectively, these data suggest that histamine promoted the cervical tumor growth through the activation of the PI3K/Akt/mTOR pathway." (PMID 32340124, 2020). "Significant increases in the expression of PI3K, Akt and mTOR, determined by immunohistochemistry analysis, were observed in the cervical tumor tissue." (PMID 32340124, 2020). "To examine the indirect chemopreventive effects of metformin that might be enhanced by nelfinavir, we analyzed key proteins of the PI3K/Akt/mTOR axis in both human cervical cell line and mouse cervical tumor tissue." (PMID 28252027, 2017).
congestive heart failure (8 papers, 2019 to 2023). Failure of the heart to pump a sufficient amount of blood to meet the needs of the body tissues, resulting in tissue congestion and edema. "This study aimed to explore whether moxibustion inhibits autophagy and reduces inflammation by regulating mTOR expression to induce myocardial protective effects and alleviate symptoms associated with chronic heart failure." (PMID 33603819, 2021). "The inhibition of mTOR via rapamycin revealed reduced apoptosis and promoted autophagy in cardiomyocytes by regulating the crosstalk between the mTOR and endoplasmic reticulum (ER) stress pathways in chronic heart failure." (PMID 37108591, 2023). "In comparison with sham animals, the model group of chronic heart failure rats showed significantly increased mTOR and phosphorylated mTOR (P-mTOR) amounts (P < 0.01, P < 0.05), which confirmed that mTOR might have an important function in CHF." (PMID 32269242, 2020).
cystinosis (8 papers, 2015 to 2025). Cystinosis is a metabolic disease characterized by an accumulation of cystine inside the lysosomes, causing damage in different organs and tissues, particularly in the kidneys and eyes. "A more recent study demonstrated downregulation of mTOR and defective lysosomal localization of this kinase after starvation/refeeding in proximal tubular cell lines from Ctns−/− mice, a model of cystinosis, an LSD and the most common cause of renal Fanconi syndrome in children." (PMID 28130275, 2017). "Cystinosin interacts with mTOR, and recently this was described as playing a major role in cell fate in cystinosis." (PMID 40943162, 2025). "The primary biochemical/physiological defect in cystinosis is failure to supply cysteine to mTOR via cystinosin." (PMID 40546328, 2025). "It has been noted that a wide range of the aberrant cell physiology in cystinosis can be explained by the disrupted mTOR pathway." (PMID 40943162, 2025). "A recent study stated that the primary biochemical/physiological defect in cystinosis is failure to supply cysteine to mammalian target of rapamycin (mTOR) via cystinosin." (PMID 40943162, 2025). "Researchers have analyzed the disease pathogenesis in depth for a strong therapeutic approach by targeting the connection between altered mTOR signaling and autophagy in cystinosis." (PMID 30717078, 2019). "Several mechanisms have been suggested to contribute to the pathogenesis of cystinosis, including lysosomal overload, endo-lysosomal transport defect, altered chaperone-mediated autophagy, mTOR signaling, transcription factor EB (TFEB) expression." (PMID 31888107, 2019). "Cystinosin had previously been described as interacting with mTOR, but its centrality in cystinosis was noted in the Berquez paper in which it was shown that proximal tubule (PT) cells in the kidney degrade disulfide containing proteins after endocytosis, generating cystine." (PMID 40546328, 2025). "Several detailed studies of autophagy in a cystinosis mouse model have been conducted; however, the autophagic flux and mTOR signaling were not well-studied." (PMID 30717078, 2019). "We show that, different from other LSDs, autophagosome number is increased, but macroautophagic flux is not impaired in cystinosis while mTOR activity is not affected." (PMID 25586965, 2015). "However, in later stages of cystinosis, due to the upstream defect in cystinosin-mediated cysteine transport, mTOR is no longer adequately activated." (PMID 40943162, 2025). "However, different from other LSDs, macroautophagy flux is not impaired in cystinosis while mTOR activity was not affected." (PMID 25586965, 2015).
demyelinating disease (8 papers, 2016 to 2026). A broad group of disorders that affect the myelin sheaths that cover the neurons. "MS and demyelinating disease can be significantly impacted by the mechanistic target of rapamycin (mTOR) pathways." (PMID 37508898, 2023). "New and innovative avenues for the investigation and treatment of demyelinating disorders are required that involve autophagy, apoptosis, FoxOs, mTOR, AMPK, SIRT1, and related systems with the APOE-ε4 gene and SARS-CoV-2." (PMID 37508898, 2023). "Recent results have shown that the phosphorylation of PI3K/AKT/mTOR pathway or activation of mTORC2 is also a helpful target in the development of remyelinating therapies for demyelinating diseases." (PMID 31030467, 2019). "Overall, this data illustrates how JCPyV activates the PI3K/AKT/mTOR pathway, yet this may have other implications in the viral-induced demyelinating disease PML." (PMID 34831441, 2021). "This review examines pharmacological targeting of PI3K/Akt/mTOR and Wnt/GSK-3β signaling and describes intracellular mechanisms involved in oligodendrocyte and neuronal differentiation, with consideration of therapeutic application in demyelinating diseases." (PMID 42274605, 2026). "Although the specific cytoplasmic signaling involved in aggresome formation has not been identified in demyelinating diseases, including CMTD, it is likely that the formation is correlated with decreased mTOR signaling." (PMID 32316234, 2020). "Although we cannot state if the described comorbidity is casual or not, some clinical and preclinical data suggest that the mTOR complex might be the link between TSC and demyelinating disease." (PMID 37176724, 2023).
developmental delay (8 papers, 2016 to 2025). "This could be explained by a known developmental delay caused by chronic mTOR inhibition during development." (PMID 28779098, 2017). "All individuals had previously undescribed variants in MTOR and clinical phenotypes consistent with SKS, including at least macrocephaly and developmental delay." (PMID 34197453, 2021). "Germline and somatic mosaic MTOR pathogenic variants cause Smith-Kingsmore Syndrome (SKS), which is characterized by macrocephaly/megalencephaly, developmental delay, intellectual disability, hypotonia, and seizures." (PMID 34197453, 2021).
diabetic encephalopathy (8 papers, 2017 to 2025). A brain disease that is characterized by functional impairment of cognition, cerebral signal conduction, neurotransmission and synaptic plasticity, and underlying structural pathology associated with diabetes. "Previous study has demonstrated that the inhibition of mTOR/NF-κB pathway could ameliorate neuroinflammation, synaptic damage, and other symptoms associated with diabetic encephalopathy." (PMID 39268468, 2024). "Besides, activating mTOR/NF-κB signaling pathway plays a critical role in the pathogenesis of diabetic encephalopathy, including neuroinflammation, synaptic protein loss, and synaptic ultrastructure impairment." (PMID 39139399, 2024). "In summary, the findings presented in this study increase our understanding of the mechanistic pathway by which mTOR-induced neuronal apoptosis may play an important causal role in the MG-induced pathogenesis of diabetic encephalopathy." (PMID 28801605, 2017). "In addition, under high glucose conditions, mTOR facilitates the translocation of NF-κB to the nucleus, promoting the production of pro-inflammatory cytokines in hippocampus neurons, highlighting the role of the mTOR/NF-κB pathway in diabetic encephalopathy." (PMID 40821823, 2025). "Targeting mTOR may provide important novel therapeutic approaches for MG-induced diabetic encephalopathy." (PMID 28801605, 2017).
disc degeneration (8 papers, 2018 to 2025). "Our findings indicate that AQP3 deficiency under hyperosmotic conditions contributes to NPC apoptosis by suppressing the PI3K/AKT/mTOR signaling pathway, potentially establishing a pathological cycle of disc degeneration." (PMID 41262548, 2025). "The roles of G3BP1 and mTOR signalling were further investigated in the in vivo disc degeneration model." (PMID 36450665, 2023). "This brief review introduces our study findings and interpretations, discussing the future applications of therapeutically modulating biological autophagy and/or mTOR signaling to treat degenerative disc disease." (PMID 32211593, 2020). "A mechanistic understanding of autophagy and mTOR signaling can provide a basis for the development of biological therapies to treat degenerative disc disease." (PMID 32211593, 2020). "Other investigators have reported that epigenetic activation of PI3K-Akt/mTOR pathway may protect against intervertebral degenerative disc disease." (PMID 36518098, 2022). "This suggests that exosomes can contribute to the recovery of the structure and function of disc degeneration and effectively promote the synthesis and secretion of the major matrix components in disc degeneration, which is achieved through the activation of the Akt-mTOR pathway." (PMID 35855812, 2022). "Furthermore, the clinical relevance of autophagy and mTOR signaling during degenerative disc disease remains largely unexplored." (PMID 32211593, 2020). "Our findings demonstrated that mammalian target of rapamycin (mTOR) signaling affects cellular senescence, catabolic and inflammatory responses, and multi-differentiation potential, suggesting that potential treatment value of rapamycin for disc degenerative diseases, especially lower back pain." (PMID 29348392, 2018). "Our findings demonstrated that mTOR signaling pathway affects AF cell senescence, catabolic and inflammatory responses, and stem cell differentiation, suggesting that potential treatment value of rapamycin for disc degenerative diseases, especially lower back pain." (PMID 29348392, 2018). "The protective roles of G3BP1 and mTOR were testified in the in vivo disc degeneration model, which may provide potential targets for IDD treatment." (PMID 36450665, 2023). "We suggest that pharmacologically targeting autophagy or gene therapy for autophagy-related genes such as mTOR, LC3, Beclin-1, p62, or other ATG genes are potential therapeutic options for degenerative disc diseases." (PMID 36009290, 2022).
Dyskinesia (8 papers, 2012 to 2024). A movement disorder which consists of effects including diminished voluntary movements and the presence of involuntary movements. "Genotype–phenotype association analysis showed that PD patients carried with MTOR gene variants exhibited milder motor symptoms but were more susceptible to dyskinesia, indicating a potential role of the MTOR gene in modulating PD phenotypes." (PMID 39354865, 2024). "Furthermore, genotype–phenotype association analysis suggested that PD patients with MTOR gene variants exhibited relatively milder motor symptoms but were more susceptible developing dyskinesia." (PMID 39354865, 2024). "Our findings supported that dysregulation of mTOR activity, as evidenced by missense variants in the MTOR gene, may contribute to PD susceptibility and dyskinesia." (PMID 39354865, 2024). "Interestingly, levodopa, the commonly used drug, causes motor side effects (dyskinesia) through activating mTOR signaling in the mouse striatum." (PMID 36247500, 2022). "In PD, for example, levodopa-induced dyskinesia is thought to be induced by D1-receptor-mediated phosphorylation of mTORC1, a hypothesis supported by the fact that genetic variability in mTOR pathway components is associated with PD dyskinesia." (PMID 32903821, 2020). "Rhes and RasGRP1 facilitate the development of L-DOPA-induced dyskinesia (LID) through the involvement of mammalian target of rapamycin (mTOR) signaling in a pre-clinical model of Parkinson's disease (PD)." (PMID 38589732, 2024). "On the other hand, SNPs in the mTOR pathway genes, BDNF, HOMER1 and DAT have been implicated in either increased or reduced risk for dyskinesias, but with single studies that are yet to be corroborated in larger cohorts." (PMID 34281267, 2021). "It was indicative of earlier animal studies that the inhibition of mTOR pathways reduces the L-dopa related dyskinesia, most likely due to impaired metabolic homeostasis." (PMID 34281267, 2021). "There is some evidence that the activation of the Mechanistic target of rapamycin (mTOR) signaling pathway contributes to L-dopa induced dyskinesia." (PMID 34281267, 2021). "In PD mouse model Rhes enhances L-DOPA-induced dyskinesia (LID), most likely through the activation of mTOR pathway." (PMID 28742811, 2017). "Activation of mTOR in striatum via Rhes, a striatal-specific small G protein, is known to mediate l-DOPA-induced dyskinesia." (PMID 23027611, 2012).
endotoxemia (8 papers, 2013 to 2023). "In a study on endotoxemia-induced acute lung injury, it was found that metformin alleviates acute lung injury caused by endotoxemia by restoring AMPK-dependent mTOR inhibition." (PMID 38283037, 2023). "Transcriptomic analysis of innate lymphocytes in the mouse model of endotoxemia suggested that NKT cells depend on the mTOR pathway in NK cells to produce IFN-γ." (PMID 36556247, 2022). "A mechanistic exploration in male C57BL/6 mice showed that endotoxemia resulted in the activation of mTOR signalling in macrophages, leading to progressive kidney inflammatory injuries and subsequent fibrosis." (PMID 32503496, 2020). "It is consistent with the report that the inhibition of Na/K-ATPase promoted myocardial TNF-α protein production and cardiac dysfunction during endotoxemia through activating Ca(2+)/CaMK/mTOR signaling." (PMID 25073093, 2014). "The administration of the mTOR inhibitor temsirolimus, even after established endotoxemia, induced autophagy and protected against the development of AKI." (PMID 23936035, 2013). "Regulation of autophagy by AMPK/mTOR pathway could also suppress endotoxemia cardiac dysfunction." (PMID 32459063, 2020). "BMSCs can eliminate endotoxemia and reduce mortality in rats with ALF, and the PI3K/AKT/mTOR signal pathway is involved in intestinal differentiation." (PMID 35122584, 2022). "In summary, we showed the therapeutic potential of BMSCs in ALF by repairing the intestinal epithelial barrier and preventing endotoxemia, and the PI3K/AKT/mTOR signaling pathway was involved in the intestinal differentiation of BMSCs." (PMID 35122584, 2022). "This is reminiscent of what was reported in a murine endotoxemia model where LPS dose-dependently induced dephosphorylation of AMPK and its target protein ACC, an event accompanied by activation (phosphorylation at T172) of mTOR in lungs of LPS injected animals." (PMID 33671212, 2021).
follicular thyroid cancer (8 papers, 2015 to 2025). "Our primary findings provide a rationale to conduct preclinical or clinical trials with mTOR inhibitor and β-elemene in follicular thyroid cancer patients." (PMID 27274989, 2016). "In the present study, we investigated the effect of a combination of mTOR inhibitor (rapamycin) and a natural antitumor plant drug (β-elemene) on follicular thyroid cancer." (PMID 27274989, 2016). "We demonstrate that the novel combination of mTOR inhibitor with β-elemene synergistically attenuates tumor cell growth in follicular thyroid cancer, which requires additional preclinical validation." (PMID 27274989, 2016). "Demonstrates the dual activation of PKA and mTOR in follicular thyroid cancers." (PMID 38074042, 2023). "Moreover, a recent study showed that follicular thyroid carcinoma tissues had decreased miR-144 expression, resulting in activated mTOR signaling, which can accelerate ovarian aging and induce POF." (PMID 25705687, 2015).
gastroenteropancreatic neuroendocrine tumors (8 papers, 2016 to 2026). "Gastrointestinal neuroendocrine tumors (GI-NETs) lack effective targeted options beyond somatostatin analogs and mTOR inhibitors." (PMID 41102405, 2025). "On the contrary, sirolimus, an agent belonging to the mTOR inhibitors, such as tacrolimus, is now studied for the treatment of lung, pancreatic, and gastrointestinal NET." (PMID 40141766, 2025). "Background: in patients with gastroenteropancreatic neuroendocrine tumors (GEP-NET), the mTOR inhibitor everolimus is associated with significant improvement in progression-free survival (PFS)." (PMID 32971877, 2020). "We therefore analyzed the status of the three axes of UPR and their relation to mTOR pathway in two gastrointestinal neuroendocrine tumors (GI-NET) cell lines STC-1 and GluTag." (PMID 28423496, 2017). "The mTOR inhibitor everolimus is currently approved for lung and gastrointestinal NET and pNET, but shows promise for use in the adjuvant setting and as combination therapy." (PMID 27539383, 2016). "mTOR inhibitors (mTORis) are Food and Drug Administration (FDA)-approved therapies for advanced gastroenteropancreatic neuroendocrine tumors (GEP-NETs), yet their clinical efficacy is often limited by transient responses and acquired resistance." (PMID 41881024, 2026).